TMEM248 (transmembrane protein 248)
Synonyms: C7orf42; FLJ10099; FLJ13090
Tractability: Antibody: UniProt predicts a signal peptide or a membrane-spanning region. PROTAC: ubiquitination databases record sites on it.
Gene: Protein-coding gene on chromosome 7 (66,921,171 to 66,958,551, forward strand). Ensembl gene ENSG00000106609.
Subcellular location: Membrane
Subcellular location (Human Protein Atlas): Vesicles
Gene Ontology:
Molecular function: protein binding
Cellular component: membrane
Genetic constraint (gnomAD): Loss-of-function variants: 9 observed, 31.27 expected, observed/expected ratio (o/e) 0.29, 90% interval 0.17 to 0.5. The upper end of that interval is the gene's LOEUF score, 0.5, which puts it in group 2 of 6, group 1 being the genes least tolerant of losing a copy. Missense variants: 338 observed, 421.57 expected, observed/expected ratio (o/e) 0.8, 90% interval 0.73 to 0.88. Synonymous variants: 184 observed, 162.83 expected, observed/expected ratio (o/e) 1.13, 90% interval 1 to 1.28.
Homologues: Orthologues: chimpanzee TMEM248 (100% identical), macaque TMEM248 (98% identical), dog TMEM248 (98% identical), pig TMEM248 (98% identical), rabbit TMEM248 (97% identical), guinea pig TMEM248 (96% identical), rat Tmem248 (95% identical), mouse Tmem248 (95% identical), tropical clawed frog tmem248 (84% identical), zebrafish tmem248 (79% identical). Paralogues in human: TMEM219 (19% identical).
Diseases named in the same sentence as TMEM248 in open-access papers:
TMEM248 is named in the same sentence as 1 disease in open-access papers, as found by Europe PMC text mining. Sharing a sentence is not in itself a finding about the gene and the disease.
TMEM248 shares sentences with these, for which no sentence is quoted: cancer (2 papers).